GPAM (glycerol-3-phosphate acyltransferase, mitochondrial)
Description:
Mitochondrial membrane protein that catalyzes the essential first step of biosynthesis of glycerolipids such as triglycerides, phosphatidic acids and lysophosphatidic acids. Esterifies acyl-group from acyl-coenzyme A (acyl-CoA) to the sn-1 position of glycerol-3-phosphate, to produce lysophosphatidic acid. Has a narrow hydrophobic binding cleft that selects for a linear acyl chain. Catalytic activity is higher for substrates with a 16-carbon acyl chain.
Synonyms: GPAT1; KIAA1560; MGC26846; GPAT
Tractability: Small molecule: a structure with a bound ligand is known. Antibody: UniProt places it where antibodies can reach, with high confidence; its Gene Ontology location is reachable by antibodies, with medium confidence. PROTAC: ubiquitination databases record sites on it; its protein half-life has been measured.
Target class: Enzyme; Transferase
Gene: Protein-coding gene on chromosome 10 (112,149,865 to 112,215,416, reverse strand). Ensembl gene ENSG00000119927.
Subcellular location: Mitochondrion outer membrane
Subcellular location (Human Protein Atlas): Mitochondria
Pathways (Reactome):
Metabolism: Activation of gene expression by SREBF (SREBP); Synthesis of PA; Triglyceride biosynthesis
Gene expression (Transcription): MLL4 and MLL3 complexes regulate expression of PPARG target genes in adipogenesis and hepatic steatosis; RUNX1 regulates estrogen receptor mediated transcription
Signal Transduction: Estrogen-dependent gene expression
Gene Ontology:
Molecular function: glycerol-3-phosphate O-acyltransferase activity; protein binding; acyltransferase activity
Biological process: phosphatidylglycerol biosynthetic process; triglyceride biosynthetic process; diacylglycerol biosynthetic process; glycerophospholipid metabolic process; phosphatidic acid biosynthetic process; CDP-diacylglycerol biosynthetic process; lipid metabolic process; phospholipid biosynthetic process
Cellular component: mitochondrion; mitochondrial outer membrane; plasma membrane
Genetic constraint (gnomAD): Loss-of-function variants: 23 observed, 43.61 expected, observed/expected ratio (o/e) 0.53, 90% interval 0.38 to 0.75. The upper end of that interval is the gene's LOEUF score, 0.75, which puts it in group 3 of 6, group 1 being the genes least tolerant of losing a copy. Missense variants: 410 observed, 494.31 expected, observed/expected ratio (o/e) 0.83, 90% interval 0.76 to 0.9. Synonymous variants: 187 observed, 178.76 expected, observed/expected ratio (o/e) 1.05, 90% interval 0.93 to 1.18.
Homologues: Orthologues: chimpanzee GPAM (99% identical), dog GPAM (96% identical), rabbit GPAM (94% identical), guinea pig GPAM (93% identical), mouse Gpam (93% identical), macaque GPAM (93% identical), pig GPAM (92% identical), rat Gpam (92% identical), tropical clawed frog gpam (70% identical), zebrafish gpam (65% identical), Drosophila melanogaster mino (26% identical), Caenorhabditis elegans acl-6 (24% identical). Paralogues in human: GPAT2 (31% identical), GNPAT (18% identical).
Diseases named in the same sentence as GPAM in open-access papers:
GPAM is named in the same sentence as 30 diseases in open-access papers, as found by Europe PMC text mining. Sharing a sentence is not in itself a finding about the gene and the disease. The quoted sentences say what the papers report.
Hepatic steatosis (14 papers, 2011 to 2024). Steatosis is a term used to denote lipid accumulation within hepatocytes. "Other previously unreported variants associated with lipid traits and fatty liver disease, including rs2792735 in GPAM, rs2980888 in TRIB1, rs13389219 in COBLL1, rs8178824 in APOH and rs339969 in ICE2." (PMID 38632349, 2024). "The missense variant in GPAM (rs2792751) encoding p.V43I was found to be significantly associated with severity of liver steatosis, while APOE rs429358 confers protection for liver steatosis." (PMID 34950105, 2021). "These gene expressions reflected the fact that CAE ameliorated hepatic steatosis by inhibiting lipogenesis, probably mediated by hepatic SREBP-1, FAS, and GPAM." (PMID 35011585, 2021). "As a reaction to elevated plasma triglycerides (TGs) and liver steatosis, hepatic miR-27b was significantly increased, and the ANGPTL3 and GPAM protein, being targets of miR-27b, were significantly repressed." (PMID 25093715, 2014).
breast carcinoma (9 papers, 2013 to 2024). "It was demonstrated that GPAM protein expression levels are linked to metabolomic and lipidomic profiles in a cohort study of human breast carcinomas." (PMID 25339452, 2015). "However, the suitability of GPAM as a therapeutic target varies among different cancer types; higher GPAM expression in breast cancer is associated with a better prognosis." (PMID 38893234, 2024). "A recent study showed that in breast cancer, GPAM expression is strongly correlated with survival rates, clinico-pathological features as well as metabolomic and lipidomic profiles." (PMID 24320595, 2013). "For example, the increased expression of GPAM has been revealed in breast cancer." (PMID 36439870, 2022). "Interestingly, the study identified the metabolite PC C34:3 as the most significantly altered metabolite with respect to GPAM expression in breast cancer patients." (PMID 24320595, 2013). "We performed bioinformatics analysis of the data from the miRDB, Targetscan, Pictar, and miRanda websets to explore the molecular mechanism of miR-27a as an oncogenic molecule in breast cancer, and found that six genes are overlapped, namely TMEM170B, GPAM, PPAP2B, ST6GALNAC3, EYA1, and PPARG." (PMID 29367600, 2018).
Obesity (7 papers, 2014 to 2026). Accumulation of substantial excess body fat. "GPAM knockout mice have reduced adiposity and its inhibition reduces food intake and increases insulin sensitivity in diet-induced obesity." (PMID 34128465, 2021).
ovarian carcinoma (7 papers, 2019 to 2024). A malignant neoplasm originating from the surface ovarian epithelium. "For instance, GPAM’s higher expression in ovarian cancer tumors is associated with a worse prognosis, making GPAM a plausible therapeutic target for ovarian cancer." (PMID 38893234, 2024). "GPAM is also a pro-cancer protein; in ovarian cancer, the expression of this protein is associated with a worse prognosis." (PMID 38893234, 2024). "Interestingly, it has been previously observed that GPAM silencing reduced cell migration and tumor xenograft development in ovarian cancer cells." (PMID 37876796, 2023). "In ovarian cancer cells, GPAM overexpression suppresses both tumor cell growth and migration." (PMID 36439870, 2022). "The expression of GPAM (glycerol-3-phosphate acyltransferase), a key enzyme in lipid biosynthesis, is increased in breast and other cancers and highly correlated with clinicopathological parameters; its inhibition reduces ovarian cancer cell migration and the growth of tumor xenograft mouse models." (PMID 35486664, 2022).
steatosis (6 papers, 2011 to 2024). Increased lipid within the cytoplasm of cells. "For instance, GPAM is highly expressed in liver, and plays role in catalyzing the first committed step in DNL as mentioned; overexpression of GPAM causes steatosis and hepatosis." (PMID 30634538, 2019). "Hepatic GPAM expression was elevated in patients with steatosis or NASH." (PMID 34327606, 2022).
Cirrhosis (5 papers, 2021 to 2024). A chronic disorder of the liver in which liver tissue becomes scarred and is partially replaced by regenerative nodules and fibrotic tissue resulting in loss of liver function. "These variants, including single nucleotide polymorphisms (SNPs) in MARC1, APOE, and GPAM, were all additionally associated with chronic liver disease and cirrhosis." (PMID 34950105, 2021). "In contrast, the missense variant p.Ile42Val (rs2792751) in GPAM had a positive effect on both ALT levels (0.006 s.d. units per allele, 95% CI: 0.005–0.007, P = 7.0 × 10−45) and cirrhosis (OR: 1.09, 95% CI: 1.06–1.12, P = 6.4 × 10−11)." (PMID 38632349, 2024). "We identified 18 sequence variants associated with NAFL and 4 with cirrhosis, and found rare, protective, predicted loss-of-function variants in MTARC1 and GPAM, underscoring them as potential drug targets." (PMID 36280732, 2022). "Genome‐wide association study (GWAS) summary statistics were extracted from seven studies (>1.7 million participants) for variants near ACVR2A, ALB, CIDEB, FOXO1, GPAM, NEAT1 and TNRC6B for: aminotransferases, liver fat, HbA1c, diagnosis of NAFLD, ARLD and cirrhosis." (PMID 35474605, 2022). "GPAM, PPP1R3B, and APOE have associations with steatosis and serum enzyme levels, but these loci have not been associated with histological features of NASH or cirrhosis." (PMID 34950105, 2021).
hepatocellular carcinoma (4 papers, 2022 to 2025). A malignant tumor that arises from hepatocytes. "miR-494-3p down-regulates the basic helix-loop-helix ARNT-like protein 1 (BMAL1) gene its involvement in aberrant lipid metabolism, thereby enhancing GPAM-mediated lipid biosynthesis in hepatocellular carcinoma (HCC) cells." (PMID 38740866, 2024). "Furthermore, in hepatocellular carcinoma, BMAL1 was shown to transcriptionally inhibit glycerol-3-phosphate acyltransferase mitochondrial (GPAM) expression in an Enhancer of zeste homolog 2 (EZH2)-dependent manner, suppressing tumor cell growth by interfering with glycolipid metabolic processes." (PMID 41228459, 2025).
Insulin resistance (4 papers, 2018 to 2024). Increased resistance towards insulin, that is, diminished effectiveness of insulin in reducing blood glucose levels. "Research on mice has demonstrated that GPAM, a specific isoform of GPAT, is implicated in insulin resistance in both muscle and the liver." (PMID 38893234, 2024). "GPAM may also be responsible for hepatic insulin resistance by participating in lipid production and has been associated with liver cirrhosis." (PMID 38893234, 2024). "The HFHFD-induced excessive blood glucose promoted insulin secretion and eventually led to insulin resistance, which triggered lipogenesis and lipid accumulation through SREBP-1 and GPAM." (PMID 36421440, 2022).
dyslipidemia (2 papers, 2017 to 2019). "They demonstrate that hepatic miR-27b is responsive to lipid levels and regulates the expression of two key metabolic genes, angiopoietin-like 3 (ANGPTL3) and glycerol-3-phosphate acyltransferase 1 (GPAM), which have been previously implicated in the pathobiology of dyslipidemia." (PMID 29286302, 2017).
liver disease (2 papers, 2022 to 2024). "In this study, we find that germline variation in only one, GPAM, was robustly associated with markers of liver disease." (PMID 35474605, 2022). "Therefore, the only somatically mutated gene for which germline variation was associated with liver disease was GPAM." (PMID 35474605, 2022). "Out of seven genomic regions with selective pressure for acquired loss of function mutations secondary to NAFLD and ARLD, only germline variation in GPAM is predictive of liver disease." (PMID 35474605, 2022).
cerebral palsy (1 paper, 2025). A group of disorders affecting the development of movement and posture, often accompanied by disturbances of sensation, perception, cognition, and behavior. "Mutations that result in the loss of GPAM function have been linked to hypomyelination in the corticospinal tract of patients with cerebral palsy." (PMID 40498018, 2025). "The GPAM knockout cell line retained a normal karyotype and exhibited pluripotent stem cell markers and differentiation capabilities similar to wild-type hESCs, making it a valuable resource for modeling the disease in brain organoids and conducting drug screening for cerebral palsy." (PMID 40498018, 2025).
E. coli infection (1 paper, 2018). "Importantly, based on our results, E. coli infection causes down-regulation of genes encoding lipid biosynthesis enzymes including ALOX15, FASN, GPAM, TM7SF2 that are involved in milk production." (PMID 29470489, 2018).
endometriosis (1 paper, 2025). The growth of functional endometrial tissue in anatomic sites outside the uterine body. "There has been limited research on the roles of ACSL5, PLA2G4A, EHHADH, GPAM, PLA2G15, SULT2A1, and ACSL3 in endometriosis, highlighting the necessity for further investigation to elucidate their contributions to its pathogenesis." (PMID 40527850, 2025).
heart failure (1 paper, 2017). Inability of the heart to pump blood at an adequate rate to meet tissue metabolic requirements. "The modules related to the metabolic process of glucose and triglycerides were detected only in heart failure arising from PPCM, with upregulated G6PC, GPAM, and PCK1." (PMID 29160422, 2017).
psoriasis (1 paper, 2015). An autoimmune condition characterized by red, well-delineated plaques with silvery scales that are usually on the extensor surfaces and scalp. "Finally, expression of glycerol-3-phosphate acyltransferase (GPAM) was significantly decreased in psoriasis lesions and our analysis revealed that GPAM recognizes PRE motifs enriched in sequences upstream of PP-decreased DEGs." (PMID 25883770, 2015). "Similarly, we identified DEG-encoded uDBPs that interact with PREs, whose function in psoriasis is presently unknown (e.g., AVEN, RBM8A, GPAM, WISP2)." (PMID 25883770, 2015). "Through in silico screening of known DNA binding sites, our findings highlight proteins not yet well studied in psoriasis, including TFs (FOXM1, EHF, SOX5) and uDBPs (AVEN, RBM8A, GPAM, WISP2)." (PMID 25883770, 2015).
type 2 diabetes (1 paper, 2024). "GPAM is involved in the metformin pathway, a drug often prescribed to treat type 2 diabetes, and a well-studied senomorphic drug." (PMID 38956648, 2024).
tumor (12 papers, 2019 to 2026). "Two variants were identified in all tumor samples situated outside the lung and three lung samples (GPAM and EPS8L2)." (PMID 36968225, 2023). "Here we found seven of the nine GPAM mutations were frameshift mutations, strongly suggestive of a tumor suppressor role." (PMID 35508466, 2022). "Furthermore, lnc-PKD2-2-3, miR-328, and GPAM were also observed to be linked with advanced tumor features such as differentiation and tumor stage in CCA patients, which result from regulation of tumor stemness, growth, and metastasis." (PMID 35965521, 2022). "Furthermore, tumor lnc-PKD2-2-3 was negatively related to miR-328 but positively linked with GPAM in CCA (both P <0.05); meanwhile, tumor miR-328 negatively related to GPAM in CCA (P <0.01)." (PMID 35965521, 2022). "BMAL1 inhibits tumor progression by suppressing glycerolipid metabolism through transcriptional inhibition of GPAM expressions in an EZH2 dependent way." (PMID 36439870, 2022). "Then it was observed that lnc-PKD2-2-3 overexpression promoted tumor volume and weight but repressed tumor apoptosis in xenograft mice; meanwhile, it increased GPAM expression but decreased miR-328 expression." (PMID 35965521, 2022). "Lnc-PKD2-2-3, miR-328, and GPAM expression in 30 pairs of CCA tumor and adjacent tissues, as well as in CCA cell lines, were determined." (PMID 35965521, 2022). "We additionally demonstrated that the anti-tumor effect of BMAL1 was dependent on the down-regulation of GPAM." (PMID 36439870, 2022). "The fact that seven of the nine GPAM mutations were frameshift mutations together with the observation that knockdown of GPAM significantly increased cell proliferation strongly suggests a tumor suppressor role for GPAM in HCC." (PMID 35508466, 2022). "Scatter plot analysis showed a negative relationship between mRNA expression levels of BMAL1 and GPAM in tumor tissues from 30 HCC individuals." (PMID 36439870, 2022). "In vivo experiments further revealed that lnc-PKD2-2-3 overexpression promoted tumor volume and weight but repressed tumor apoptosis in xenograft mice; meanwhile, it increased GPAM expression but decreased miR-328 expression (all P <0.05)." (PMID 35965521, 2022). "Significantly, only 1 methylation curve of FITM1 or GPAM was gathered, indicating that the hypermethylated status of FITM1 and GPAM were centralized and common in tumor samples." (PMID 32174969, 2020). "The remaining three subpopulations, namely MLB (86.0%), GPAM+ macrophages (74.2%), and APOC2+ macrophages (87.7%), were significantly enriched in the pCR group, suggesting potential anti-tumor or ICB-sensitizing roles." (PMID 41514936, 2026). "By validation using RT-qPCR in 30 CCA patients, it was observed that lnc-PKD2-2-3 and GPAM were elevated, whereas miR-328 was reduced in CCA tumor tissues compared with adjacent tissues (all P <0.01)." (PMID 35965521, 2022). "Similarly, a negative relationship between the protein expression levels of BMAL1 and GPAM was observed in 217 HCC tissues and 36-unpaired primary and metastasis tumor tissues from HCC patients." (PMID 36439870, 2022). "Subsequently, their expressions in CCA patients were detected in the present study, which observed that lnc-PKD2-2-3 and GPAM were elevated, while miR-328 was reduced in CCA tumor tissues compared to adjacent tissues, and they were closely inter-correlated with each other." (PMID 35965521, 2022). "Low expression of FITM1, ABCG5, BSCL2, and GPAM in non-viral HCC tumor specimens generally predicted worse survival status." (PMID 32174969, 2020).
cancer (6 papers, 2020 to 2024). A tumor composed of atypical neoplastic, often pleomorphic cells that invade other tissues. "Four GPATs have been discovered; nevertheless, only GPAT1 (GPAM) has been related to cancer outcome." (PMID 33194695, 2020).
GPAM also shares sentences with these, for which no sentence is quoted: hypertriglyceridaemia (2 papers); liver cancer (2); cholangiocarcinoma (1); coronary artery disease (1); glioblastoma (1); Hyperinsulinemia (1); hypothyroidism (1); infection (1); nonalcoholic fatty liver disease (1); overnutrition (1); prostate carcinoma (1); renal carcinoma (1).